HIF1A (hypoxia inducible factor 1 subunit alpha)
Diseases named in the same sentence as HIF1A in open-access papers (continued):
Sharing a sentence is not in itself a finding about the gene and the disease.
breast cancer (continued). "Hes1 regulates breast cancer cell proliferation, EMT, and invasion through multiple pathways such as Notch, AKT, STAT, and HIF-1α." (PMID 40755759, 2025). "G-protein–coupled estrogen receptor (GPER), a transcriptional target of HIF-1α, mediates a feedforward loop involving IL-1β–induced CAF activation and IL1R1 expression in breast cancer cells, jointly regulating target genes and relevant biological processes." (PMID 40813760, 2025). "A novel study showed an interplay between macrophages and breast cancer cells through the TME, introducing HIF-1α-stabilizing long noncoding RNA, lactate, and PHD2." (PMID 39757165, 2025). "We observed a similar scenario in HER2-positive breast cancer, where our data confirm that low WWOX/HIF1A ratios intensify oncogenic signalling." (PMID 41007296, 2025). "Phytochemicals from MO demonstrated strong interactions with HIF-1α (hypoxia-inducible factor 1-alpha), VEGF, and GLUT1 receptors, showing favorable pharmacokinetics and potential as breast cancer inhibitors." (PMID 40149610, 2025). "Specifically, in basal-like breast cancer, we observed that low WWOX/HIF1A ratios correlate with upregulation of key proliferative pathways—including PI3K-Akt, MAPK, Ras, and ErbB signalling—which collectively drive tumour aggressiveness and rapid growth." (PMID 41007296, 2025). "In breast cancer, suppression of SENP1 activity diminishes deSUMOylation of HIF‐1α, culminating in HIF‐1α degradation and inhibition of cancer metastasis." (PMID 39205481, 2024). "The interaction between TOR1B and metabolic pathways, as well as its regulation by HIF-1α, suggests its significance in adapting to hypoxia, thereby positioning TOR1B as a promising therapeutic target for aggressive breast cancer subtypes." (PMID 38842687, 2024). "This study also reveals that SETDB1-mediated PLK3 K106/200 methylation not only serves as a key signal driving HIF1α stability and BCSC properties but also acts as a prognostic factor for metastatic breast cancer patients." (PMID 38520019, 2024). "HIF-1α promotes collagen crosslinking, increasing ECM stiffness and providing a more favorable mechanical environment for invasion and metastasis in breast cancer." (PMID 39684583, 2024). "Integrin α11 which was consistently up-regulated by cooperative interactions of HIF1α, GLI-1, and EZH2 in a positive feedback circuit, resulted in drug resistance, CSC increase and EMT in breast cancer cells." (PMID 38664825, 2024). "When MCF-7 and T-47D breast cancer cell lines were cultured in 1% O2 for 8–24 h, ESR1 mRNA was significantly reduced as a consequence of transcriptional repression in a HIF-1α-dependent manner." (PMID 39282472, 2024). "Like most solid tumors, breast cancer is highly vascularized due to elevated production of soluble pro-angiogenic signals, such as VEGF and FGF that are downstream of HIF-1α in precursor lesions and early-stage cancer." (PMID 39439572, 2024). "Our research investigated the impact of miR-561-3p on the expression of ZEB1, HIF1A and MYC in breast cancer cells for the first time." (PMID 38462658, 2024). "In human breast cancer cell lines, sirtuin 3 (SIRT3), a member of the sirtuin family, acts by indirectly destabilizing HIF1-α, thus inhibiting glycolysis." (PMID 38790264, 2024). "Such an association between hypoxia and CD44 induction is supported by previous studies that demonstrated HIF‐1α transcriptional activation of CD44 in nucleus pulposus cells and co‐localization of hypoxia and CD44 expression in breast cancer xenografts." (PMID 37849446, 2024). "Briefly, SRC-1 promotes the transcriptional activityof several transcription factors, including HOXC11, PEA3, AP-1, HIF1α, c-FOS, Ets1/2, and STAT1/3, in breast cancer." (PMID 38553750, 2024).
breast cancer (continued). "Similarly, another study showed that exercise during doxorubicin treatment of mouse breast cancer could also decrease tumor hypoxemia, as evidenced by reduced HIF1-α and HIF2-α, and enhance the antitumor effect when tumor growth was compared to untreated animals." (PMID 38725573, 2024). "The results showed the potential of PTS to downregulate CAIX, HIF-1α and VEGF, while upregulating the expression of apoptosis-related proteins, thus inhibiting breast cancer growth and metastasis in this patient group." (PMID 38920676, 2024). "Surprisingly, this certainly confirms the in silico results which also show that Seagrass E. acoroides has superior potential in fighting HIF-1A, EGFR tyrosine kinase, and HER2 as manifestation markers of breast cancer." (PMID 38474594, 2024). "The molecular mechanism involves inhibiting hypoxia-inducible factor 1-alpha (HIF-1α) and heat shock protein 90 (HSP90) expression while increasing ROS levels, confirming the radiosensitizing effect of curcumin on breast cancer." (PMID 38993643, 2024). "Our observations revealed significantly elevated endogenous HIF-1α expression in both Hs578T (stage III) and MDA-MB-231 (stage IV) breast cancer cell lines compared to the MCF-7 (stage I) cell line." (PMID 38339408, 2024). "Compared with that in normal tissues, the expression of CDK4, HIF1A, and MALAT1 were upregulated in the breast cancer samples, which was consistent with the results of CARM1." (PMID 38476024, 2024). "In breast cancer, ALKBH5 expression is induced by hypoxia‐inducible factor 1α (HIF1α) and HIF1β, and its overexpression under hypoxic conditions reduces NANOG mRNA methylation levels, increasing the number of breast cancer stem cells." (PMID 39445003, 2024). "The upregulation of NRF2 stimulates the expression of G6PD and activates HIF-1α, resulting in NOTCH1 signaling activation and breast cancer proliferation." (PMID 38424190, 2024). "These elevated levels of ROS subsequently promote HIF-1α activity, which further induces aerobic glycolysis and reduces OXPHOS activity in breast cancer cells." (PMID 39472438, 2024). "Research conducted on breast cancer cells demonstrated the cooperative effect of upregulated NRF2 and HIF-1α on cell proliferation, which led to the enhancement of glycolytic genes, including hexokinase 2, pyruvate kinase M2, and lactate dehydrogenase A98." (PMID 38424190, 2024). "Prolonged exposure (72 h) of breast cancer cell lines show stable HIF-2α protein accumulation, whereas HIF-1α was abundant after 6 h of hypoxia and declined at 72 h." (PMID 39282472, 2024). "The m6A demethylase ALKBH5 is a direct target of HIF-1α and HIF-2α and is hypoxic regulated in a variety of cell lines, including breast cancer and adipocytes." (PMID 38227578, 2024). "sEVs secreted by breast cancer-associated tumor macrophages (TAMs) transfer a specific lncRNA, HIF1α-stabilizing lncRNA (HISLA), to breast cancer cells." (PMID 39403606, 2024). "NRF2 overexpression and KEAP1 knockdown promoted the expression of G6PD and HIF-1α/NOTCH1 to induce EMT and breast cancer migration." (PMID 38424190, 2024). "In colon cancer cells, it has been observed that HIF‐1α‐induced autophagy increased cellular radioresistance, but also that HIF‐1α siRNA increased the radiosensitivity of breast cancer cells due to a reduction in autophagy." (PMID 38899556, 2024). "A recent study has shown that CBD can inhibit breast cancer growth by inhibiting SRC activity, thereby upregulating VHL expression, reducing HIF-1α synthesis in breast cancer cells, and inhibiting angiogenesis." (PMID 38731434, 2024). "It binds to HIF-1α and promotes HIF-1α degradation through ubiquitination, thereby inhibiting breast cancer cell metastasis." (PMID 39408813, 2024). "Building upon these findings, our research has demonstrated that TNFAIP2 can induce the transcription of HIF1α via the Rac1-ERK-AP1 signaling pathway, thereby promoting tumor angiogenesis in breast cancer." (PMID 39532855, 2024).
breast cancer (continued). "Knockdown of circABCB10 led to decreased protein levels of glycolysis-related factors, such as HIF1a, HK2, and LDHA, resulting in enhanced radiosensitivity of breast cancer cells." (PMID 38408962, 2024). "In breast cancer, SENP1 inhibition prevents the deSUMOylation of hypoxia-inducible factor 1α (HIF-1α), ultimately leading to HIF-1α degradation and cancer metastasis suppression." (PMID 38389923, 2024). "The expression patterns of HIF-1α and UBE2M were opposite in these two types of breast cancer cell lines." (PMID 39138151, 2024). "Molecular mechanism studies revealed that isoliquiritigenin promotes HIF-1α proteasome degradation, resulting in a significant inhibition of VEGF expression in mammary carcinoma." (PMID 38611849, 2024). "In breast cancer, PRKN targets HIF-1α for ubiquitination, controlling its stability and resulting in metastasis suppression." (PMID 37190124, 2023). "Among them, circRNF20 binds to miR-487a and promotes the expression of HIF-1α, thereby upregulating HK2 levels and accelerating the Warburg effect in breast cancer cells." (PMID 37204526, 2023). "It was reported that the reduction in the gap junction and HIF1α and CXCR4 expression significantly inhibited the metastasis of breast cancer cells." (PMID 37511481, 2023). "In breast cancer cells and in HL-1 cardiomyocytes, hypoxia increased the expression and activity of G protein-coupled receptor 30 (GPR30) in HIF-1α-dependent manner." (PMID 37886965, 2023). "In turn, lactic acid triggers the HIF-1α/STAT3 axis in M2-like TAMs leading to the release of EGF and subsequent activation of EGFR/PI3K/AKT in breast cancer cells to elevate the expression of SGLT1 and promotion of drug resistance." (PMID 37900137, 2023). "In breast cancer, miR-21 facilitates CSC metastasis by upregulating mesenchymal markers or synergistically regulating HIF-1α mRNA." (PMID 37853437, 2023). "Similar observations were made in breast cancer cells, where EGCG suppressed the activation of hypoxia-inducible factor 1-alpha (HIF-1α) and NFκB as well as VEGF expression." (PMID 37446908, 2023). "In agreement, inspection of clinical breast cancer data from TCGA–Metabric showed a striking inverse correlation of PML and HIF1a." (PMID 37518985, 2023). "displayed that targeted binding of FBXW7 to miR-182 attenuates the proteasomal degradation of VEGF and HIF-1α, while reduced VEGF turnover promotes breast cancer angiogenesis and invasion." (PMID 37658431, 2023). "HIF-1α is the principal regulator of hypoxia, and is also led to autophagy activation with BNIP3 in breast cancer." (PMID 36937439, 2023). "Under hypoxia, PHF6 interacts with HIF1α/HIF-2α to promote their recruitment to the HRE, thereby driving breast cancer progression." (PMID 36967443, 2023). "The Co-IP assay demonstrated the physical interactions between endogenous HIF1α/2α and PHF6 in hypoxic breast cancer cells." (PMID 36967443, 2023). "In contrast, in vesicles with high levels of miR-7641, miR-7641 inhibited HIF-1α to downregulate the levels of HK2, GLUT1, and LDHA to suppress glycolysis in breast cancer." (PMID 37204526, 2023). "Hypoxia up-regulates the transcription target of HIF-1α, namely G protein estrogen receptor (GPER), that makes CAF-induced IL-1β to express IL1R1 in breast cancer cells." (PMID 36226050, 2022). "AXL was also shown to regulate HIF-1α levels, thus contributing to the hypoxic response in HER2+ breast cancer cells." (PMID 35158733, 2022). "This compound, by decreasing mRNA and protein levels of HIF-1α and downregulating Nrf2, can trigger ROS-induced apoptosis in MDA-MB-231 breast cancer cells." (PMID 36289931, 2022). "While this induced hypoxia-related genes such as HIF1α in SGBS cells, co-culture induces genes of endothelial-to-mesenchymal transition in MCF-7 cells, supporting an important role of obesity in driving breast cancer aggressiveness." (PMID 35986215, 2022).
breast cancer (continued). "HIF-1α stable long non-coding RNA (HISLA) enhances aerobic glycolysis and apoptosis resistance in breast cancer cells." (PMID 35801079, 2022). "In ER-positive breast cancer cell lines, T47D and MCF7 knockdown of HIF-1α resulted in decreased ER-α and increased ER-β levels, although the second one got reduced after 48 h of hypoxia." (PMID 36139678, 2022). "Breast cancer cells, MDA-MB-231 treated with paclitaxel showed HIF-1α dependent, down- or up-regulation of the expression of several pro-and anti-apoptotic genes." (PMID 36139678, 2022). "HIF-1α activated NOTCH signaling, and NOTCH1 increased HIF-1α expression in ovarian and breast cancer cell lines." (PMID 35681691, 2022). "X-C Motif chemokine Ligand 1 (XCL1) enhanced expression of HIF-1α and phosphorylation of extracellular signal-regulated kinase (ERK) 1/2, which induces EMT and imposes migration of breast cancer cells." (PMID 36226050, 2022). "In a recent study, HIF-1α-specific IgG was shown to be elevated in TNBC patients and immunization against HIF-1α inhibited the growth of basal-like mammary tumors." (PMID 36230969, 2022). "Mechanistically, circRNF20 competitively binds to miR-487a and elevates HIF-1α expression and promotes the transcription of hexokinase II (HK2), thereby regulating the Warburg effect and proliferation of breast cancer cells." (PMID 35563687, 2022). "In summary, here we present seminal findings that DLEU1, by activating HIF-1α-induced transcription of CKAP2, promotes malignant growth and metastatic spread of breast cancer." (PMID 35853854, 2022). "For instance, bFGF triggers HIF-1α activation and VEGF-A release via the PI3K/AKT and MEK transduction pathways in normoxic breast cancer cells." (PMID 35158804, 2022). "LncRNA PCAT-1, elevated in breast cancer patients, directly interacts with the activated protein C kinase-1 (RACK1) protein to prevent RACK1 binding to HIF-1α, thereby protecting HIF-1α from RACK1-induced oxygen-dependent degradation of lncRNA." (PMID 36226050, 2022). "Meanwhile, AKT inhibition by MK-2206 reduced the expression of HIF-1α and ACE2 in both parental and resistant breast cancer cells." (PMID 36335375, 2022). "HIF-1α regulated many molecules involved in EMT, for example, HIF-1α regulated TGFβ1/SMAD3 signaling pathway, promoting breast cancer metastasis." (PMID 36226050, 2022). "To interrogate the efficacy of HIF1α/HDAC1/EZH2 inhibitors in vivo, we used the immune-competent syngeneic 4T1 murine breast tumor model that closely mimics human TNBC breast cancer tumorigenesis." (PMID 35840558, 2022). "Silencing of HIF-2α, instead of HIF-1α, markedly attenuates the hypoxic elevation of RAB11B-AS1 expression in breast cancer cells." (PMID 35842651, 2022). "Similarly, in breast cancer patients, high HP-[1-13C]pyruvate to HP-[1-13C]lactate conversion rates identified strongly glycolytic aggressive triple negative breast cancer with high HIF1a and MCT1 tissue expression and high-grade lesions in prostate cancer with increased MCT4 expression." (PMID 36494842, 2022). "Ten years ago functional cooperation between HIF-1α and GPER was demonstrated in cardiomyocytes and breast cancer cells." (PMID 35740412, 2022). "In breast cancer, HMGA1, EGF and TGFβ signaling pathways, HIF-1α all promoted EMT by upregulating FOXM1." (PMID 35197112, 2022). "Conversely, suppression of YB-1 impeded the enhanced expression of HIF1α and CAIX in tumours generated from both de novo transformed primary cells as well as established breast cancer cell lines." (PMID 34294889, 2022). "The ability of estrogenic GPER signaling to trigger HIF-1α-mediated VEGF expression has been reported as supporting angiogenesis and progression in breast cancer." (PMID 35740412, 2022). "To investigate the metabolic preference in breast cancer cell lines, we evaluated the expression of AMPK and HIF1α, which have been considered key modulators of oxidative and glycolytic metabolism, respectively." (PMID 35327574, 2022).
breast cancer (continued). "In breast cancer cells, it was shown that the overexpression of Nrf2 augments the expression of Notch1 via G6PD/HIF-1α pathway." (PMID 35417854, 2022). "Taken together, these results suggest that EPI-induced expression of HIF-1α and ACE2 in breast cancer cells is highly dependent on ROS-mediated AKT activation." (PMID 36335375, 2022). "In breast cancer, P4HA1 can regulate HIF-1α expression via regulating α-KG and succinate levels, which promotes chemoresistance by regulating the HIF-1–dependent cancer cell stemness." (PMID 35812752, 2022). "ERα and ERβ are activated after binding to estrogen, form dimers, and bind to target genes such as CCND1, HIF1A, and IL6, which have a role in breast cancer proliferation." (PMID 36106139, 2022). "In general, the HIF-1α-JFK axis enhances cell tolerance to hypoxia, promotes breast cancer cell survival." (PMID 36226050, 2022). "Oxygen-independent regulation of HIF-1α through PI3K/AKT and rapamycin has also been shown to occur in breast cancer cells upon treatment with the ErbB3/ErbB4 ligand heregulin, which stimulates HIF-1α synthesis and VEGF-A expression." (PMID 35158804, 2022). "Mechanistically, chemotherapeutic agents induce ACE2 expression in breast cancer cells by increasing intracellular ROS production, while increased ROS levels enhance AKT phosphorylation and subsequently upregulate HIF-1α expression." (PMID 36335375, 2022). "Accordingly, select ER modulators downregulate VEGF-induced angiogenesis by suppressing HIF-1α/VEGFR2 signaling as well as the activation of AKT and ERK axes in breast cancer cells." (PMID 35158804, 2022). "In breast cancer cells, ZMYND8 interacts with HIF1A and HIF2A by binding to the HREs H3K14ac and H4K16ac; subsequently, the ZMYND8/HIF axis increases breast tumor angiogenesis and decreases cancer cell death to promote metastasis." (PMID 35659268, 2022). "We mainly focused on the general activation of HIF-1α signaling by ATP in MDA-MB-231 and MCF-7 cells, providing a relatively broad array of targets for breast cancer therapy." (PMID 35236823, 2022). "Considering that hypoxia promotes HIF-1α-mediated transcription and secretion of IGF-II, it is perhaps unsurprising that HIF-1α inhibitors decrease IGF-II signaling and trigger anti-migratory effects in breast cancer cells." (PMID 35158804, 2022). "This experiment was performed by Zhang and his coworkers in 2018, who found higher levels of Nrf2 and HIF-1α mRNA and proteins in MCF-7 and MDA-MB-231 breast cancer cells than in normal breast cells (MCF-10A)." (PMID 35571115, 2022). "Hypoxia induced HIF1α positively regulates SLC38A1 and SLC38A2 expression in adipose cells during obesity and in breast cancer cells, respectively." (PMID 36613847, 2022). "HIF1A and HIF-2α can transcriptionally activate hypoxia-responsive lncRNA MALAT1 to enhance the migration of breast cancer cells." (PMID 36230902, 2022). "Oroxylin A suppresses the glycolysis-dependent proliferation of breast cancer MDA-MB-231 cells by activating SRT3, and decreasing HIF-1α-targeted HK2 gene transcription." (PMID 36339566, 2022). "Interaction signals of Ifi204 with HIF1α and that with PRMT2 were clearly observed in almost 80% of adipocytes adjacent to mammary tumor cells." (PMID 35593921, 2022). "Overall, the knockdown of CircRNF20 seems to be an efficient way to reduce miR-487a/HIF-1α/HK2-mediated glycolysis and the proliferation of breast cancer cells." (PMID 36230935, 2022). "LncRNA MALAT1 in hypoxia response can be transcriptionally activated by HIF-1α and HIF-2α, acting as a molecular sponge for miR-3064-5p to promote tumor growth and migration of breast cancer cells." (PMID 36226050, 2022). "Collectively, these data suggest that HIF-1α is required for chemotherapeutic agent-induced, ROS-mediated ACE2 expression in breast cancer cells." (PMID 36335375, 2022).